FAT1 (FAT atypical cadherin 1)
Description:
[Protocadherin Fat 1]: Plays an essential role for cellular polarization, directed cell migration and modulating cell-cell contact.
Synonyms: CDHF7; FAT; CDHR8; ME5; hFat1
Tractability: Antibody: UniProt places it where antibodies can reach, with high confidence; its Gene Ontology location is reachable by antibodies, with high confidence; UniProt predicts a signal peptide or a membrane-spanning region. PROTAC: ubiquitination databases record sites on it; its protein half-life has been measured.
Gene: Protein-coding gene on chromosome 4 (186,587,791 to 186,726,722, reverse strand). Ensembl gene ENSG00000083857.
Subcellular location: Cell membrane (Protocadherin Fat 1); Nucleus (Protocadherin Fat 1, nuclear form)
Gene Ontology:
Molecular function: protein binding; calcium ion binding
Biological process: anatomical structure morphogenesis; cell adhesion; cell migration; cell-cell adhesion mediated by cadherin; cell-cell signaling; cellular response to angiotensin; homophilic cell-cell adhesion; positive regulation of vascular associated smooth muscle cell migration
Cellular component: cell-cell junction; extracellular exosome; focal adhesion; nucleus; perinuclear region of cytoplasm; plasma membrane; adherens junction; cytosol; membrane
Genetic constraint (gnomAD): Loss-of-function variants: 164 observed, 327.21 expected, observed/expected ratio (o/e) 0.5, 90% interval 0.44 to 0.57. The upper end of that interval is the gene's LOEUF score, 0.57, which puts it in group 2 of 6, group 1 being the genes least tolerant of losing a copy. Missense variants: 5,630 observed, 5,997.2 expected, observed/expected ratio (o/e) 0.94, 90% interval 0.92 to 0.96. Synonymous variants: 2,219 observed, 2,317.8 expected, observed/expected ratio (o/e) 0.96, 90% interval 0.92 to 0.99.
Gene-disease validity (ClinGen):
ClinGen rates the evidence that FAT1 causes each of these diseases.
focal segmental glomerulosclerosis (autosomal recessive): Strong. A renal disorder characterized by sclerotic lesions in the glomeruli.
Cancer hallmarks: suppression of growth (promotes); escaping programmed cell death (promotes); invasion and metastasis (promotes); invasion and metastasis (suppresses)
Homologues: Orthologues: chimpanzee FAT1 (99% identical), macaque FAT1 (96% identical), rabbit FAT1 (92% identical), dog FAT1 (91% identical), guinea pig FAT1 (91% identical), mouse Fat1 (88% identical), rat Fat1 (88% identical), tropical clawed frog fat1 (73% identical), zebrafish fat1a (65% identical), zebrafish fat1b (53% identical), Caenorhabditis elegans hmr-1 (15% identical), Drosophila melanogaster stan (12% identical), and 2 more. Paralogues in human: FAT3 (52% identical), FAT2 (42% identical), FAT4 (27% identical), CELSR1 (14% identical), CELSR3 (13% identical), CELSR2 (13% identical).
Diseases named in the same sentence as FAT1 in open-access papers:
FAT1 is named in the same sentence as 197 diseases in open-access papers, as found by Europe PMC text mining. Sharing a sentence is not in itself a finding about the gene and the disease. The quoted sentences say what the papers report.
breast carcinoma (49 papers, 2011 to 2026). "The preceding findings prompted us to examine associations between FAT1 expression and breast cancer pathological and molecular classifications." (PMID 40083689, 2025). "Patients with biallelic FAT1 inactivation experience a significantly shorter PFS of 2.4 months, compared to 10.1 months in ER+ breast cancer patients with FAT1 missense mutations and 11.3 months in patients with wild-type FAT1." (PMID 40244377, 2025). "Among the different subtypes in the TCGA database, FAT1 gave strong scoring associations with immune subtypes in breast cancer (BRCA) with its high expression most closely associated with the TGF-β dominant immune subclassification." (PMID 40083689, 2025). "With these reports in mind, we revisited the topic of FAT1 in breast cancer to examine clinicopathological associations." (PMID 40083689, 2025). "Only ~5% of breast cancer cases had FAT1 mutations, with gene amplifications and deep deletions being rare while missense mutations (either shallow or diploid) were more common including a small number of truncating mutations." (PMID 40083689, 2025). "In sum, these findings indicate FAT1 expression decreases with breast cancer transformation and is associated with increased promoter methylation." (PMID 40083689, 2025). "On balance, these findings suggest that different patient outcomes are associated with FAT1 expression according to breast cancer subtype." (PMID 40083689, 2025). "With respect to FAT1, as noted in the Introduction, some cancers such as pancreatic adenocarcinomas overexpress FAT1 57 while studies in breast cancer provide mixed conclusions, with reports of mutational loss contrasting with findings of overexpression." (PMID 40083689, 2025). "We observed diversification among breast cancer subtypes where FAT1 was most highly expressed in TNBC/Basal-like breast cancers where its higher expression was associated with worsened patient outcomes." (PMID 40083689, 2025). "To explore the paradigm of FAT1 loss in breast cancer, we began by analyzing its cell-type- expression in the breast." (PMID 40083689, 2025). "Outside activation of the MAPK pathway, RB1 loss and FAT1 loss were recently reported to contribute to CDK4i/6i resistance in ER+ breast cancers." (PMID 38066089, 2024). "A previous study reported that FAT1 loss in breast cancer cells induced YAP activation, promoting CDK4/6 inhibitor resistance." (PMID 38622197, 2024). "FAT1 loss-of-function mutations have been associated with drug resistance in patients with ER+ breast cancer treated with CDK 4/6 inhibitors via a mechanism involving the Hippo pathway and changes in gene expression caused by YAP129." (PMID 37147285, 2023). "In breast cancer, decreased FAT1 expression has been associated with high histological grade, poor lymph node status, progression, aggressive behavior, and poor prognosis." (PMID 37147285, 2023). "In the last 10 years, several publications have reported a correlation between FAT1 mutation or expression with prognosis in different type of cancers, such as breast cancer, NSCLC, gastric cancer, and T-cell lymphoma." (PMID 35965328, 2022). "A genomic analysis of estrogen receptor-positive (ER+) breast cancer identified that loss of FAT1 causes Hippo signaling pathway suppression and subsequent YAP/TAZ activation." (PMID 33467099, 2021). "The loss of FAT1 (Protocadherin Fat1) seems to be involved in Hippo activation in chemo-resistant breast cancer cells." (PMID 32210163, 2020). "The loss of FAT1 also contributes to the mechanism of resistance mediated by CDK4/6i in ER+ breast cancer." (PMID 31822636, 2019). "Future studies will aim to determine whether combination treatment can suppress β-catenin nuclear translocation and restore chemosensitivity in FAT1-deficient breast cancer cells." (PMID 41362743, 2026). "However, the precise role and underlying mechanisms of FAT1 in breast cancer (BC) remain insufficiently explored." (PMID 41362743, 2026).
breast carcinoma (continued). "FAT1 cadherin exhibits dual tumor suppressor and oncogenic roles across various cancers, but its function in breast cancer remains unclear due to conflicting reports of mutational loss and overexpression." (PMID 40083689, 2025). "Additionally, FAT atypical cadherin 1 (FAT1) is highly expressed in breast cancer tissues or cells and is associated with a poor prognosis." (PMID 37781700, 2023). "Together these findings provide new perspectives regarding the role of FAT1 in breast cancer, also laying a foundation for further exploration of the role of FAT1 in the development and progression of TNBC." (PMID 40083689, 2025). "In general agreement with these findings, SCA analysis of primary breast cancer tissues showed that FAT1 expression predominately aligned with cancer cells from TNBC and HER2 cases but not the luminal A and luminal B subtypes." (PMID 40083689, 2025). "Although rare, loss-of-function mutations in the cadherin superfamily member FAT1 have also been associated with CDK4/6is resistance, potentially due to CDK6 overexpression in ER+ breast cancer patients." (PMID 40244377, 2025). "Nevertheless, not all genes display good correlation between mRNA and protein levels in breast cancer tissues 38, but importantly we found the subtype variations in FAT1 mRNA expression were maintained at the protein level with the highest levels in TNBC." (PMID 40083689, 2025). "Cross comparisons of the breast cancer datasets from the TCGA and GTEx resources showed decreased FAT1 mRNA expression in malignant tissues." (PMID 40083689, 2025). "Previous studies have reported that the expression of FAT1 is downregulated in breast tumor tissues compared to normal tissues, and it is also reduced in breast cancer cells relative to normal mammary epithelial cells." (PMID 41230499, 2025). "Hippo signaling in ER+ breast cancer is an established tumor suppressor in ER+ MBC, and FAT1 loss serves as a mechanism of resistance to CDK4/6i." (PMID 35804935, 2022). "Loss of FAT1 was also associated with poor outcome on CDK4/6i therapy, although inactivating mutations in FAT1 are rare in advanced ER+ breast cancer." (PMID 32940689, 2021). "FAT1 knockdown in glioblastoma cell lines resulted in promotion of cell cycle progression and cellular growth and in a breast cancer xenograft model FAT1 knockdown resulted in the progression of ductal carcinoma in situ to invasive breast cancer." (PMID 35047999, 2021). "Conversely, many genes frequently mutated in MPA/DMBA-induced tumors, such as ATR, FAT1, and KRAS, are rarely mutated in breast cancer." (PMID 31366361, 2019). "For example, over-expression of the FAT1 was observed in different tumors including in DCIS breast cancer, melanoma and leukemia." (PMID 30538721, 2018). "FAT1 was reported to be overexpressed in breast cancer, in melanoma in leukemia, and in pancreatic cancer." (PMID 30416985, 2018). "Our study first shows the direct in vivo evidence that DHA can suppress lung metastasis of breast cancer in Fat-1 transgenic mice model." (PMID 27363023, 2016). "Studies have directly analyzed Fat1 expression and found overexpression in breast cancer, melanoma and leukemia, suggesting a tumor promoting effect of Fat1." (PMID 24625754, 2014). "Notably, we observed marked downregulation of FAT1 expression in LECs cultured on tumor stiffness-mimicking matrix, a finding validated in clinical breast cancer specimens and murine models of breast cancer and melanoma." (PMID 41230499, 2025). "In addition, CP-10 was tested in two independent palbociclib-resistant breast cancer cell lines with CDK6 copy amplification (MCF-7 CDK6N2) and FAT1 loss (MCF-7 FAT1 CR), where it successfully induced CDK6 degradation and inhibited proliferation." (PMID 40793752, 2025). "We then considered whether FAT1 was differentially expressed in normal versus primary breast cancer tissues." (PMID 40083689, 2025).
breast carcinoma (continued). "Taken together, the low frequency and lack of recurrent FAT1 mutations is unlikely to be responsible for the changes in FAT1 mRNA expression between normal and breast cancer tissues." (PMID 40083689, 2025). "In the murine 4T1 breast cancer model, immunofluorescence co-staining with the lymphatic-specific marker podoplanin (PDPN) and FAT1 revealed a significant reduction in FAT1 fluorescence intensity within tumor-associated lymphatic vessels compared to those in normal mammary tissue." (PMID 41230499, 2025). "Thus, FAT1 is clearly detectable in secretory epithelial cells whose subsets are considered the cell of origin of breast cancer." (PMID 40083689, 2025). "FAT1 is clearly detectable in secretory epithelial cells whose subsets are considered the cell of origin of breast cancer 33 while its overall levels appear reduced in breast cancer tissues." (PMID 40083689, 2025). "To assess whether our 3D system recapitulate the resistance of breast cancer cells to CDK4/6 inhibitors and endocrine therapy, which is associated with low FAT1 levels and Hippo pathway activation, we conducted a comparative analysis of gene expression data." (PMID 38565950, 2024). "FAT1 protein expression was significantly higher in clear cell renal cell carcinoma, colon cancer, and uterine corpus endometrial carcinoma and was significantly lower in breast cancer." (PMID 36517565, 2022). "In a genomic analysis of breast cancers that were resistant to CDK4/6 inhibitors, loss-of-function mutations were found in the FAT1 gene, and the knockout of FAT1 conferred resistance to CDK4/6 inhibitors by the overexpression of the CDK6 protein via the suppression of the Hippo pathway." (PMID 35681048, 2022). "Therefore, elevated CDK6 expression confers resistance to CDK4/6 inhibitors in breast cancer cells with FAT1 inactivation." (PMID 33467099, 2021). "Thus, Li and coworkers have analyzed 348 ER+ breast cancers that were treated with CDK4/6 inhibitors and identified loss-of-function mutations at the level of FAT1 and RB1 genes in association with drug resistance." (PMID 32210163, 2020). "Accordingly, n-3 PUFAs induced apoptosis in breast cancer cells in vitro and in a Fat-1 mice breast cancer model, by inhibition of the MEK/ERK/Bad signaling pathway; the inhibition was induced through the increased expression of the integral membrane protein syndecan-1 (SDC-1)." (PMID 26821053, 2016). "Whether the increased n-3 PUFA would protect Fat-1 mice against breast cancer remains to be studied." (PMID 21655218, 2011). "Thus, based on pathological and molecular features, high FAT1 expression in breast cancer is most closely associated with ER/PR negative and TNBC/basal-like cases while lowest FAT1 expression occurs the ER+ and luminal B classifications." (PMID 40083689, 2025). "Subtype-specific analysis reveals that high FAT1 expression correlates with poor outcomes in basal-like/triple-negative breast cancer (TNBC), while elevated FAT1 expression in luminal A/estrogen receptor-positive breast cancers is associated with improved patient prognosis." (PMID 40083689, 2025). "Moreover, high FAT1 expression was found to align with treatment response signatures with bioinformatic analyses suggesting that FAT1 is involved in establishing an immunosuppressive microenvironment within breast cancer lesions." (PMID 40083689, 2025). "Moreover, loss or inactivating mutations in the FAT1 tumor suppressor gene, which normally inhibits Hippo signaling, led to the enrichment of YAP/TAZ transcription factors on the CDK6 promoter, ultimately causing CDK6 amplification and resistance to CDK4/6is in ER+ breast cancer." (PMID 40244377, 2025). "These included several well-known cancer genes or their family members with previously less recognized role in breast cancer—FGFR3, FGFR4, NOTCH3, KMT2B, EP300, FLT4 and FAT1." (PMID 40858906, 2025).
breast carcinoma (continued). "For breast cancer patients, known oncogenes and tumor suppressor genes such as ESR1, KRAS, PIK3CA, PIK3R1, FAT1, and MED12 were consistently identified in both ctDNA and tumor WES across patients." (PMID 37878600, 2023). "To test whether FAT1-mediated regulation of YAP/TAZ protein levels is a more general mechanism, we analyzed the breast cancer cell line MDA-MB-231 and the glioblastoma cell line U-87 transfected with control siRNA and siRNA directed against FAT1." (PMID 40478800, 2025).
head and neck squamous cell carcinoma (30 papers, 2016 to 2025). A squamous cell carcinoma that arises from any of the following anatomic sites: lip and oral cavity, nasal cavity, paranasal sinuses, pharynx, larynx, and salivary glands. "FAT1 is commonly mutated in human cancers (~20% in head and neck squamous cell carcinoma) and deletions accelerate tumor initiation and malignant progression and promote tumor stemness and spontaneous metastasis in cSCC models." (PMID 40507266, 2025). "FAT atypical cadherin 1 (FAT1) has a mutation rate of approximately 22.79% in head and neck squamous cell carcinoma (HNSCC), second only to that of TP535-7." (PMID 39781458, 2025). "Reportedly, inactivating mutations in the FAT1 gene potentially activated the Wnt signaling pathway and promoted the carcinogenesis, such as in head and neck squamous cell carcinomas." (PMID 36076209, 2022). "Compared to the other types of cancers, NOTCH1 and FAT1 have a relatively high nonsense mutation rate in head and neck squamous cell carcinoma (HNSCC)." (PMID 36428516, 2022). "By conducting a database search, we found that another two tumor suppressor genes, NOTCH1 and FAT1, have a high nonsense mutation rate in head and neck squamous cell carcinoma (HNSCC)." (PMID 36428516, 2022). "In our study, we classified patients with head and neck squamous cell carcinoma (HNSCC) as FAT1‐associated low risk and FAT1‐associated high risk, based on our predefined FAT1 gene‐related molecular signature." (PMID 34939311, 2022). "High mutation frequency in the FAT1 exclusively associated with HPV-negative head and neck squamous cell carcinoma (HNSCC)." (PMID 30657779, 2019). "Case 1 contained a mutation in the tumor suppressor FAT1 atypical cadherin gene, which has been implicated in glioblastoma, colorectal adenocarcinoma, and head and neck squamous cell carcinoma." (PMID 27175596, 2016). "A comprehensive proteomics and drug screening study in pan-cancer models confirmed that FAT1 mutations in head and neck squamous cell carcinoma (HNSCC) sensitize cells to the BET inhibitor JQ1, whereas esophageal squamous cell carcinoma (ESCC) and other cancers exhibit different resistance patterns." (PMID 40242237, 2025). "The study of Hippo Yap pathway in head and neck squamous cell carcinoma showed that overexpression of PIK3CA (phosphatidylinositol 3-kinase catalytic subunit α) or the loss of FAT1 (fatty atypical cadherin 1) function could lead to the activation of yap." (PMID 33413358, 2021). "FAT1 had the highest mutation frequency in head and neck squamous cell carcinoma, suggesting that FAT1 mutation might play an important role in the occurrence and development of OSCC." (PMID 34950653, 2021). "FAT atypical cadherin 1 (FAT1) is one of the most frequently mutated genes in head and neck squamous cell carcinoma (HNSCC), exhibiting the highest mutation rate across different tumor types." (PMID 40407216, 2025). "FAT1 is a tumor suppressor gene encoding the protocadherin FAT1, which has been found to be mutated in different types of human cancers with the highest frequency in head and neck squamous cell carcinoma (HNSCC)." (PMID 40478800, 2025). "On the other hand, in head and neck squamous cell carcinoma, FAT1 loss-of-function mutations are associated with decreased FAT1 expression in tumors; interestingly, FAT1 knockdown increases migration and invasion in head and neck squamous cell carcinoma cell lines." (PMID 37371091, 2023). "FAT atypical cadherin 1 (FAT1), which encodes an atypical cadherin-coding protein, has a high mutation rate and is commonly regarded as a tumor suppressor gene in head and neck squamous cell carcinoma (HNSCC)." (PMID 39781458, 2025).